Y_RNA (Y RNA )
Gene: Miscellaneous RNA gene on chromosome X (12,054,824 to 12,054,926, reverse strand). Ensembl gene ENSG00000206792.
Homologues: Orthologues: chimpanzee Y_RNA (99% identical), macaque Y_RNA (93% identical), guinea pig Y_RNA (88% identical). Paralogues in human: Y_RNA (88% identical), RNY1 (86% identical), Y_RNA (86% identical), Y_RNA (85% identical), RNY1P11 (84% identical), Y_RNA (84% identical), Y_RNA (83% identical), RNY1P10 (83% identical), RNY1P12 (83% identical), RNY1P8 (82% identical), Y_RNA (82% identical), RNY1P5 (81% identical), and 99 more.